Y_RNA (Y RNA )
Gene: Miscellaneous RNA gene on chromosome 11 (3,663,815 to 3,663,911, reverse strand). Ensembl gene ENSG00000201279.
Homologues: Orthologues: chimpanzee Y_RNA (100% identical), macaque Y_RNA (91% identical). Paralogues in human: RNY4P37 (90% identical), RNY4P7 (88% identical), RNY4P9 (88% identical), RNY4 (87% identical), Y_RNA (87% identical), RNY4P36 (86% identical), RNY4P6 (86% identical), Y_RNA (86% identical), RNY4P10 (85% identical), RNY4P25 (85% identical), RNY4P3 (85% identical), Y_RNA (85% identical), and 89 more.